TOPBP1 (DNA topoisomerase II binding protein 1)
Diseases named in the same sentence as TOPBP1 in open-access papers (continued):
Sharing a sentence is not in itself a finding about the gene and the disease.
cancer (continued). "In cancer cells, the levels of TopBP1 affect the amplitude of Chk1 activation in response to DNA damage." (PMID 33556369, 2021). "It appears that the levels of TopBP1 in the Ad-TopBP1-infected MDA-MB468-shTopBP1 cells were either comparable with or within twofold higher or lower than those expressed in the three cancer lines or tumor tissues." (PMID 33556369, 2021). "The result is very relevant in cancer, since a modest reduction of TopBP1 level in cancer cells that highly express TopBP1 can enhance S-phase checkpoint response to replicative stress." (PMID 33556369, 2021). "By reconstitution of TopBP1 in the TopBP1-deleted cancer cells with different MOI of Ad-TopBP1, we demonstrate that low levels of TopBP1 stimulate, but high levels of TopBP1 inhibit, Chk1 activation." (PMID 33556369, 2021). "Here we uncover an unexpected biphasic concentration-dependent response of ATR/Chk1 activation controlled by the levels of TopBP1 in cancer cells." (PMID 33556369, 2021). "We next used the fraction of genome altered in each sample as an index for genomic instability to investigate its correlation with TopBP1 expression across all cancer types in PanCancer TCGA datasets." (PMID 33556369, 2021). "Our findings indicate that higher expression of TopBP1 in PCa is correlated with advanced cancer status and poor prognosis." (PMID 32459662, 2020). "Analysis of these genes revealed significant upregulation in APE1, BRCA1, Chk1, Chk2, and TopBP1 for all cancer types." (PMID 32111912, 2020). "Although Top2a knockout mice have not been described, Topbp1 knockouts die at the same early stage of embryogenesis as Brg1 null homozygotes, and TOPBP1 is involved in normal DNA replication as well as cancer prevention." (PMID 25544751, 2015). "Certainly, amplification of ATR and TOPBP1 has been separated in other carcinomas and the trend in the TCGA database is towards inactivation of ATM kinase signaling and increased ATR kinase signaling." (PMID 26438152, 2015). "ATR (located on human chromosome 3q22-q24) and TOPBP1 (located on human chromosome 3q22.1) are co-amplified in 11 carcinomas." (PMID 26438152, 2015). "The expression levels of TopBP1 and Claspin were increased in the cancer cells that survived radiation therapy." (PMID 25216549, 2014). "We found that the expression levels of TopBP1 and Claspin were significantly increased in the surviving cancer cells after radiation therapy compared to untreated cells." (PMID 25216549, 2014). "Functional analyses in vitro and in vivo indicated that the expression TopBP1 and Claspin positively affects the survival of cancer cells and thus negatively the xenograft metastasis model animals." (PMID 25216549, 2014). "Functional analyses indicated that the expression TopBP1 and Claspin positively affects the survival of cancer cells and thus negatively the xenograft metastasis model animals in response to radiation." (PMID 25216549, 2014). "The most striking feature of TopBP1 is that it has eight BRCA1 C-terminal (BRCT) domains which were first identified in breast cancer gene 1 (BRCA1)." (PMID 23277395, 2013). "The inhibition of TopBP1 expression by antisense oligomers or by siRNA induces apoptosis in cancer cell lines or MEF cells." (PMID 23950734, 2013). "In case of 50 cancer samples TopBP1 mRNA expression was analyzed both in FFPE sections and fresh breast tissues." (PMID 22544570, 2012). "We also found in normal tissue mainly nuclear localization of TopBP1 whereas in most cancer tissue samples TopBP1 localized also in cytoplasmic compartment." (PMID 22544570, 2012). "The results of our present study surprisingly showed lower level of TopBP1 mRNA in cancer samples compared to normal tissues." (PMID 22544570, 2012). "Expression of TopBP1 protein was also examined using Western blot, in both normal breast tissue and carcinoma specimens in 24 and 50 cases, respectively." (PMID 22544570, 2012).
cancer (continued). "Although quinacrine targets multiple pathways, interference with TopBP1 condensate formation and DNA lesion signaling may represent a key mechanism of its preferential toxicity toward cancer cells." (PMID 41190242, 2025). "During breast tumorigenesis, highly expressed TOPBP1 may help cancer cells efficiently cope with the sustained replication stress by compartmentalizing itself and associated factors around ATR." (PMID 41392982, 2025). "Following Topbp1 knockdown, we hypothesized that olaparib effectively impedes cancer growth in an orthotopic model utilizing the Patu8988 cell line." (PMID 39920847, 2025). "We found very good correlations between TopBP1 expression and Fraction Genome Altered in the majority of cancer types in PanCancer TCGA and METABRIC breast dataset, suggesting that this association is a general phenomenon among different cancer types." (PMID 33556369, 2021). "Therapy that can reduce TopBP1 levels might refortify the checkpoint response in many cancers that overexpress TopBP1." (PMID 33556369, 2021). "Many cancer cells express high levels of TopBP1 in part due to deregulation of the Rb/E2F pathway." (PMID 33556369, 2021). "Alterations in expression of TopBP1 have been reported to be related to other cancers." (PMID 32459662, 2020). "Given the many roles of TOPBP1 in maintaining cell viability in the presence of the genomic instability that typically accompanies cancer progression, pharmacological disruption of TOPBP1-BRCT interactions with ligand proteins offers an attractive therapeutic approach." (PMID 30295604, 2018). "In our study, TOPBP1 was found to be up regulated in cancer tissues and related to survival." (PMID 29108269, 2017). "TOPBP1 has been reported to accelerate tumor development in multi-cancers." (PMID 29108269, 2017). "In contrast, the co-amplification of ATR (located on human chromosome 3q22-q24) and TOPBP1 (located on human chromosome 3q22.1) in 11 carcinomas may increase ATR activity." (PMID 26438152, 2015). "There is possibility that in cancer cells TopBP1 is more stable and can be accumulated." (PMID 22544570, 2012). "Several genes encoding protein products that are important in cancer and have functions related to cell cycle, growth, DNA replication and protein translation (such as CCND1, TOP2A, TOPBP1, TFRC; three members of H4 histone family [HIST1H4C, HIST1H4B, and HIST1H4E]; and EIF4G1)." (PMID 17498291, 2007). "Here we investigated how TopBP1 overexpression may affect the ATR/Chk1 activation in cancer cells." (PMID 33556369, 2021). "However, the pattern of TopBP1 staining in human breast tissues changed from predominantly nuclear in normal epithelium, to nuclear and cytoplasmic or purely cytoplasmic in most of cancers." (PMID 22544570, 2012). "The cancer associated biological function of some were known little about, such as CBX2, CBX5, CDT1, TOPBP1 and RUNX2, but whose implication in cancer worth further exploration based on emerging evidences." (PMID 37917664, 2023). "Cancers displaying unfavorable risk with high ALT (BRCA, SARC, and LUAD) may be regulated by the transcriptional factors E2F4, TFDP1, E2F1, E2F7, and SIN3A (FDR = 0.001) in the DNA repair pathway, including genes repairing DNA damage such as CENPI, CLSPN, TOPBP1, and MCM4." (PMID 32784588, 2020). "Furthermore, a positive correlation was detected between TOPBP1 expression and the ATR pathway in the cellular context of PDAC cancer cell lines." (PMID 39920847, 2025). "Treatment with this drug has the potential to destabilize HPV16 E2 as it would disrupt interaction with TopBP1 and promote integration of the HPV16 genome, which could promote HPV16 cancer development." (PMID 36840558, 2023). "Although a role for TopBP1 in ATR/Chk1 activation in normal cells is well established, the significance of TopBP1 overexpression in ATR/Chk1 activation in cancer cells expressing high levels of TopBP1 has not been investigated." (PMID 33556369, 2021).
cancer (continued). "If the levels of TopBP1 are higher than the optimal level for ATR activation, these cancer cells may, to some extent, become defective in checkpoint response to replicative stress." (PMID 33556369, 2021). "In addition, the cancer genome atlas (TCGA) database was interrogated for alterations in: 1) ATM, MRE11A, RAD50 and NBN; 2) ATR, ATRIP and TOPBP1; and 3) 15 FA genes." (PMID 26438152, 2015). "TOPBP1 and ATR are amplified independently in 1 and 12 carcinomas, respectively." (PMID 26438152, 2015). "The mean level of TopBP1 in homogenates was higher in cancer samples compared to normal cells (p < 0.05)." (PMID 22544570, 2012). "Notably, APE1 forms biomolecular condensates in vitro and in nucleoli independent of its nuclease activity to promote the ATR-Chk1 DDR pathway activation in cancer cells, and APE1 is proposed as a new direct activator of the ATR kinase, in addition to TopBP1 and ETAA1." (PMID 37216274, 2023). "Thus, in cancer cells with high levels of endogenous TopBP1, modest but not high-efficient knockdown of TopBP1 can render cells more responsive to replicative stress to halt DNA synthesis and allow repair of DNA damage as in normal cells." (PMID 33556369, 2021). "As such, some cancer cells may not have appropriate checkpoint response owing to a high level of TopBP1." (PMID 33556369, 2021). "Thus, many cancer cells may not have full functionality of ATR response owing to overexpression of TopBP1." (PMID 33556369, 2021). "Given the lack of established TOPBP1 inhibitors, AZD6738—a potent ATR kinase inhibitor —has garnered significant interest in cancer research." (PMID 39920847, 2025). "Here we demonstrate that the degree of ATR/Chk1 activation is regulated by TopBP1 in a biphasic, concentration-dependent manner in a nontransformed MCF10A cell line and several cancer cell lines, including H1299, MDA-MB468, and U2OS." (PMID 33556369, 2021). "However, the impact of TopBP1 overexpression on ATR/Chk1 activation and cancer development has not been investigated." (PMID 33556369, 2021).
tumor (21 papers, 2012 to 2026). "Copy number variation analysis showed that CSNK2A1, HTATSF1, and TOPBP1 gain copy number and their amplification is tightly associated with expression, suggesting a possible genomic cooption for the three genes during tumor evolution." (PMID 38762174, 2024). "Building on the observation that TOPBP1 may be a potential “HRDness inducer,” we used olaparib, typically administered to HR-deficient tumor patients, and narrowed its use to 5–7% of patients with PDAC with a pathogenic germline BRCA mutation, aiming to establish a new PDAC treatment strategy." (PMID 39920847, 2025). "With growing interest in exploiting mitotic DSB repair as a therapeutic vulnerability in HR deficient tumours, we hypothesised that the function of TOPBP1 in mediating protein-protein interactions throughout the cell cycle may be especially critical during mitosis." (PMID 41309571, 2025). "Our study highlights the previously unrecognized role of TopBP1 as a co-regulator of lineage-defining transcription factors and as a determinant of Flt3L-mediated anti-tumor efficacy." (PMID 42104014, 2026). "Mice with DC-specific depletion of TopBP1 (TopBP1cKO) exhibited accelerated tumor progression due to impaired anti-tumor immunity, which was characterized by cDC deficiency and pre-DC accumulation." (PMID 42104014, 2026). "We then investigated the genes and pathways associated with responses to olaparib treatment and TOPBP1 knockdown on DNA damage and PDAC tumor cell proliferation through RNA sequencing." (PMID 39920847, 2025). "A significant reduction in tumor volumes was observed in the olaparib-treated mice injected with Topbp1-knockdown Patu8988 cells compared to those in the vehicle group." (PMID 39920847, 2025). "We showed that both sgRNA-1 and sgRNA-2 cells were characterized by a significantly reduced ability to load TOPBP1 and RAD51 and were more susceptible to cisplatin or talazoparib, as well as reduced tumor volume or weight." (PMID 38762174, 2024). "In the remaining 20 tumor samples in grade II, TopBP1 protein was also detected in cytoplasmic fraction." (PMID 22544570, 2012). "Moreover, the Ki67-based mitotic proliferation index demonstrated that olaparib effectively inhibited tumor growth in mice injected with Topbp1-knockdown Patu8988 cells." (PMID 39920847, 2025). "High TopBP1 expression may contribute to tumor development by reducing the strength of ATR/Chk1 activation." (PMID 33556369, 2021). "Expression of TopBP1 protein was also correlated with histological grade of neoplasms." (PMID 23277395, 2013). "All tumor samples classified as grade I and grade II showed TopBP1 protein expression." (PMID 22544570, 2012). "TOPBP1 and CDC45 play an important role in DNA replication, and MTBP plays a critical role in promoting the growth and migration of tumor cells." (PMID 37266876, 2024). "We herein provide a prototype strategy to prevent TOPBP1 condensate assembly for innovative therapeutic interventions, and further studies are needed to fully exploit and utilize the potential of TOPBP1 LLPS in tumor management." (PMID 41392982, 2025). "In addition, OTUD6A inhibits TopBP1 ubiquitination by disrupting the interaction between TopBP1 and UBR5 and promotes tumour cell resistance to chemoradiotherapy." (PMID 38685067, 2024).
tumor (continued). "Interestingly, low or moderate levels of TopBP1 correlate with normal ATR/Chk1 activation during stress, but TopBP1 overexpression has an inhibitory effect on ATR/Chk1 activation, which, in theory, would promote the resistance of tumor cells to DNA damage by suppressing apoptosis." (PMID 35897913, 2022).
infection (2 papers, 2021 to 2023). The state of being infected such as from the introduction of a foreign agent such as serum, vaccine, antigenic substance or organism. "More ATR was coimmunoprecipitated with TopBP1 when TopBP1 levels were increased by Ad-TopBP1 infection from an MOI of 100 to 200, coinciding with the increased Chk1 phosphorylation." (PMID 33556369, 2021). "To further support this notion, we reconstituted TopBP1 in one of the MDA-MB468 cell lines that showed modest knockdown of TopBP1 (shTopBP1-1A cells) by Ad-TopBP1 infection at various MOIs, such that their TopBP1 expression was lower or close to that in the shScr control cells." (PMID 33556369, 2021). "Moreover, chromatin binding assay demonstrated that ATR binding to chromatin was significantly decreased when TopBP1 was highly expressed by Ad-TopBP1 infection at an MOI of 400, concurrent with an increase of chromatin-associated TopBP1 and a declining level of Chk1 phosphorylation." (PMID 33556369, 2021). "To confirm that NS1 is an alternative marker for cellular DDR during all stages of MVM infection, we performed laser microirradiation followed by immunofluorescence for NS1 and phosphorylated CHK1, which is activated downstream of ATR/TopBP1." (PMID 37376543, 2023).
TOPBP1 also shares sentences with these, for which no sentence is quoted: lobular carcinoma (2 papers); adenoma (1); ataxia telangiectasia (1); colorectal tumors (1); hematological malignancies (1); hepatocellular carcinoma (1); leukemia (1); lymphopenia (1); Lynch syndrome (1); male infertility (1); microcephalic primordial dwarfism (1); non-small cell lung carcinoma (1); Telangiectasia (1); teratoma (1); triple-negative breast carcinoma (1).